MIR499A (microRNA 499a)
Synonyms: hsa-mir-499; MIR499; MIRN499; hsa-mir-499a; mir-499a
Gene: MicroRNA gene on chromosome 20 (34,990,376 to 34,990,497, forward strand). Ensembl gene ENSG00000207635.
Gene Ontology:
Biological process: miRNA-mediated post-transcriptional gene silencing
Cellular component: RISC complex
Diseases named in the same sentence as MIR499A in open-access papers:
MIR499A is named in the same sentence as 2 diseases in open-access papers, as found by Europe PMC text mining. Sharing a sentence is not in itself a finding about the gene and the disease. The quoted sentences say what the papers report.
hypertrophic cardiomyopathy (1 paper, 2025). A condition in which the myocardium is hypertrophied without an obvious cause. "Variants in MYH7B, which hosts MIR499a, have been associated with both hypertrophic cardiomyopathy and oxidative stress–related metabolic pathways." (PMID 41226486, 2025).
MIR499A also shares sentences with these, for which no sentence is quoted: rheumatoid arthritis (1 paper).